AVP (arginine vasopressin)
Diseases named in the same sentence as AVP in open-access papers (continued):
Sharing a sentence is not in itself a finding about the gene and the disease.
Hyponatremia (continued). "SIADH refers to euvolemic states of hyponatremia due to impaired water excretion resulting from nonphysiologic stimuli for arginine vasopressin (AVP) /antidiuretic hormone (ADH) production." (PMID 38163817, 2024). "If Ou is between the lower and upper limit in scenario B, then it can be concluded that while a certain degree of AVP is present, it is merely contributory, rather than explanatory, for the observed hyponatremia." (PMID 38584119, 2024). "Second, we did not collect data on several factors affecting hyponatremia, including fluid imbalances, medications, presence of heart failure, arginine vasopressin levels, and urine osmolality." (PMID 38618394, 2024). "Other explanations include hyponatraemia, either from the syndrome of inappropriate antidiuretic hormone secretion (SIADH) or cerebral salt wasting syndrome, and fluid overload, both of which also stimulate AVP release." (PMID 38957516, 2024). "Pro-inflammatory cytokines like interleukin-1β and IL-6 are believed to stimulate the secretion of arginine vasopressin, leading to the syndrome of inappropriate antidiuretic hormone (ADH) secretion (SIADH), which may contribute to hyponatremia in COVID-19." (PMID 39451561, 2024). "AVP manages serum osmolality via V2 receptors and hence AQP-2 water channels of the renal epithelial cells of collecting ducts are stimulated with the V2- vasopressin receptor and therefore leads to water retention and hyponatremia." (PMID 38812639, 2024). "Not every degree of inappropriate AVP release can be considered a solely sufficient explanation for hyponatremia." (PMID 38584119, 2024). "The weakened myocardium reduces cardiac output, which sequentially decreases the effective circulating volume; increases AVP production via baroreceptor-mediated non-osmotic stimuli; and increases renal water reabsorption, which induces hyponatremia." (PMID 36836016, 2023). "Both AVP and OXT neurons demonstrate structural and functional adaptions to physiological challenges such as dehydration, changes in physiological state such as pregnancy, and pathophysiological states such as hypertension or hyponatremia." (PMID 37858270, 2023). "Most patients with chronic hyponatremia exhibit elevated levels of AVP that are inconsistent with the osmotic balance, even when SIAD is not the underlying cause of hyponatremia." (PMID 37992803, 2023). "Taking into consideration that plasma osmolality in heart failure is normal or low, the predominance of non-osmotic AVP secretion over osmotic AVP secretion plays the main role in the development of hyponatremia." (PMID 36675801, 2023). "The predominance of non-osmotic AVP secretion over osmotic AVP release plays a crucial role in developing water imbalance and hyponatremia in CHF." (PMID 37508636, 2023). "Most cases of euvolaemic or hypervolaemic hyponatraemia are perpetuated by non-osmotic release of arginine vasopressin (AVP, also known as antidiuretic hormone (ADH)), causing water retention." (PMID 35449020, 2022). "In rats with liver cirrhosis, differences between males and females in AVP release were also detected which provided an explanation for females not developing hyponatremia in that study." (PMID 36434506, 2022). "Hyponatremia was rare and no alteration was detected in the ADH/AVP secretion (reflected by copeptin levels) of our patient population with short-term severe hypothyroidism." (PMID 36187132, 2022). "Interventional studies were performed in hypervolemic hyponatremia where the non-osmotic release of AVP is triggered by baroreceptors-induced stimuli secondary to organ dysfunction." (PMID 35678906, 2022). "Hyponatremia in oncology is a negative prognosis factor because this occurs due to Syndrome of Inappropriate Antidiuretic Hormone (SIADH) excessive production of arginine vasopressin by tumors or anticancer effects." (PMID 36304376, 2022).
Hyponatremia (continued). "This situation is not transposable to hypovolemic or euvolemic hyponatremia such as syndrome of the inappropriate release of AVP (SIADH)." (PMID 35678906, 2022). "Significantly increased AVP levels have been reported in patients with HF (acute HF with hyponatremia and chronic HF with or without hyponatremia) and LV dysfunction." (PMID 35859595, 2022). "The crucial form in this work is hypervolemic hyponatremia, which can result from the overconsumption of fluids, likely in combination with non-osmotic stimulation of AVP secretion, and damage to the heart, liver, and kidney." (PMID 36431252, 2022). "By acting on V2-R present in the CD of kidneys, the increased AVP levels stimulate cAMP production, leading to the insertion of AQP2 into the apical membrane of CD, resulting in higher levels of water reabsorption, lower levels of diuresis, and hyponatremia." (PMID 34880830, 2021). "In brief, drug-induced hyponatremia can be largely explained by AQP2 upregulation from V2R-cAMP-PKA signaling in the absence of AVP stimulation." (PMID 34955900, 2021). "In the second phase, alcohol, like MDMA or rather the MDMA-metabolite HMMA, increases AVP production, which may further increase MDMA-induced (severe) hyponatremia." (PMID 34554408, 2021). "Given NSAIDs inhibit prostaglandin synthesis, NSAIDs were thought to induce the SIADH; currently, potentiation of AVP action but not enhanced AVP release is considered as the most plausible explanation for NSAID-induced hyponatremia." (PMID 34955900, 2021). "Because non-suppressed plasma AVP levels were found in only a minority of these patients, the NSIAD was suggested as the underlying mechanism of SSRI-induced hyponatremia in most patients." (PMID 34955900, 2021). "However, the SIAD is now considered to be the correct expression for the mechanism of drug-induced hyponatremia because the SIADH and NSIAD share the same clinical features, but present with different plasma AVP levels." (PMID 34955900, 2021). "Of note, when non-osmotic AVP secretion is present, or when sodium losses are severe, modest water ingestion at rates of 1–2 L/h can induce symptomatic hyponatremia." (PMID 31284689, 2019). "The present paper demonstrated that exaggerated release of AVP plays a crucial role as an accessory endocrine disorder in pathological states of water retention and dilutional hyponatremia in non-endocrine disorders." (PMID 29088071, 2017). "The rationale for treating this patient was to treat the hyponatraemia and presumed excessive AVP secretion (plasma copeptin was not measured) and secondly to prevent or reduce renal growth as much as possible." (PMID 28194574, 2017). "In SIADH, late stage heart failure, and liver cirrhosis elevated levels of AVP lead to diluted plasma with hyponatremia with or without hypervolemia." (PMID 26903868, 2016). "Hospitalized children have numerous hemodynamic and non-hemodynamic stimuli for arginine vasopressin (AVP) production, which place them at risk for developing hyponatremia." (PMID 27610358, 2016). "Stroke is often complicated by uncontrolled secretion of arginine-vasopressin (AVP) and hyponatremia, which may have deleterious effects on the brain." (PMID 26275173, 2015). "If the symptoms or signs of water intoxication are more severe, the hyponatremia can be corrected by nonpeptide arginine vasopressin (AVP) antagonists that block the antidiuretic effect of AVP." (PMID 24558627, 2013). "However, our findings reinforce that increased AVP release in hypotonic hyponatremia is clinically significant, independent of the degree of electrolyte disturbance." (PMID 40317183, 2025). "Duloxetine-induced hyponatremia has been considered to occur from the syndrome of inappropriate antidiuretic hormone secretion (SIADH), but it is unclear whether duloxetine stimulates arginine vasopressin release from the posterior pituitary gland." (PMID 39202754, 2024).
Hyponatremia (continued). "Therefore, AVP release has to concentrate urine to at least Ou>3.3·Na+p in order to produce and/or aggravate hyponatremia without the necessity for EFWI>0." (PMID 38584119, 2024). "Furthermore, arginine vasopressin, which is often responsible for hyponatremia, did not affect FGF23 production." (PMID 37992803, 2023). "However, the circulating levels of arginine vasopressin are often not elevated or too unstable to evaluate during hypotonic hyponatremia, such as SIADH." (PMID 36247169, 2022). "Abnormal release of AVP from the pituitary gland or non-pituitary sources causes the syndrome of inappropriate antidiuretic hormone secretion (SIADH), a condition characterized by water body deregulation and hyponatremia." (PMID 35874817, 2022). "Hyponatremia in oncology is a negative prognosis factor because this occurs due to syndrome of inappropriate antidiuretic hormone (SIADH), causing excessive production of arginine vasopressin by tumors or anticancer effects." (PMID 36304376, 2022). "Because non-suppressed plasma AVP levels were detected in only a minority of these patients, nephrogenic antidiuresis or NSIAD was suggested as the underlying mechanism of SSRI-induced hyponatremia in most patients." (PMID 36233678, 2022). "Conversely, hypovolemia, e.g. due to diuretic medication, may lead to hypotension as a trigger for an appropriate non-osmotic AVP release, possibly leading to a dilutional hyponatremia as well." (PMID 32912147, 2020). "Mild hyponatremia in our study was usually measured immediately after febrile seizure in the emergency room, thus, which is thought to be due to febrile illness or mild dehydration rather than excessive arginine vasopressin secretion." (PMID 30193581, 2018). "The finding that plasma AVP is not suppressed in pregnancy in the presence of hyponatremia and hypotonicity supports this hypothesis." (PMID 24803942, 2014). "Plasma AVP concentrations were higher in patients with clinical SIADH than in any other patients with hyponatremia, including those with acute glucocorticoid insufficiency, those with hyponatremia due to inappropriate intravenous fluid administration and those with hypovolemic hyponatremia." (PMID 26237593, 2014). "Could this aldosterone-independent AVP-stimulation of ENaC (in the presence of activated AQP2) be contributing to the draw of water out of the collecting duct and thus, be contributing to the hyponatremia common to adrenal insufficiency?" (PMID 22934055, 2012). "It should be noted that hyponatremia will spontaneously and rapidly improve by removing the cause(s) of non-osmotic AVP secretion (e.g., ECF volume depletion, vomiting, and pain), even if urine ([Na+] + [K+]) is above serum [Na+] in cases of AVP secretion due to non-osmotic stimuli." (PMID 39847311, 2025). "Furthermore, immersion may also stimulate non-osmotic release of arginine vasopressin (AVP), impairing the kidneys’ ability to excrete free water and predisposing to water retention and hyponatremia." (PMID 40385252, 2025). "While analyzing hypotonic hyponatremia, it is imperative to not only verify whether or not a certain degree of inappropriate AVP release is present, but also to ascertain whether it—in itself—could sufficiently explain the observed hyponatremia, as these two are not always synonymous." (PMID 38584119, 2024). "Various conditions have been associated with hyponatremia, including chronic heart failure, chronic kidney disease, liver cirrhosis, diuretic treatment and the Syndrome of Inappropriate Antidiuresis (SIAD), in which AVP secretion occurs in the absence of an osmotic or hemodynamic abnormality." (PMID 34880830, 2021). "In 2015, the Third International Exercise-Associated Hyponatremia Consensus Development Conference concluded that the primary etiology and mechanism leading to EAH was the overconsumption of hypotonic fluids likely in combination with non-osmotic stimulation of AVP secretion." (PMID 28316971, 2017).
Hyponatremia (continued). "Exercise-associated hyponatremia (EAH) was initially described in the 1980s in endurance athletes, and work done since then has conclusively identified that overdrinking beyond thirst and non-osmotic arginine vasopressin release are the most common etiologic factors." (PMID 28316971, 2017). "Despite normal or low plasma osmolality, SIAD is characterized by the non-osmotic production of arginine vasopressin (AVP), which results in concentrated urine, dilutional hyponatremia, and decreased free water excretion." (PMID 41416267, 2025). "The mechanism by which SSRIs, such as fluoxetine and sertraline, can induce hyponatremia has been explored in experimental studies, and it was found that they upregulate aquaporin-2 (AQP2) in the kidney without arginine vasopressin." (PMID 39202754, 2024). "Indeed, hyponatremia in cirrhosis results from an impairment of effective volemia, mostly due to peripheral arterial vasodilation, leading to both non-osmotic, volume-driven AVP secretion and reduced renal perfusion and glomerular filtration rate that impair free-water clearance." (PMID 26237020, 2014). "Increased levels of cytokines, such as IL-6, may directly stimulate non-osmotic release of arginine vasopressin (AVP), the predominant mechanism triggering hyponatremia in pediatric patients with MIS-C." (PMID 39451561, 2024). "The non-osmotic arginine vasopressin (AVP), the renin-angiotensin-aldosterone axis, and the sympathetic nervous system activate vascular resistance and enhance sodium and water renal retention, leading to hyponatremia in hospitalized patients with HF." (PMID 34680582, 2021). "Hyponatremia in advanced CKD patients, who have no ability to concentrate urine in response to AVP, was still independently related with mortality after adjusting for other risk factors, indicating that hyponatremia may be directly toxic." (PMID 29499058, 2018).
diabetes insipidus (161 papers, 2008 to 2026). A disorder characterized by excretion of large amounts of urine, accompanied by excessive thirst. "Combined deficiency of ERAD and autophagy in AVP neurons exacerbated the diabetes insipidus phenotype compared with either gene deficiency, and increased the sensitivity to osmotic stress‐induced animal death." (PMID 40051383, 2025). "Dexmedetomidine has also been reported, albeit rarely, to cause transient diabetes insipidus-like water diuresis through the α2-adrenergic suppression of hypothalamic AVP release." (PMID 41375697, 2025). "The Working Group for Renaming Diabetes Insipidus has recommended changing the name of central diabetes insipidus to AVP deficiency and nephrogenic diabetes insipidus to AVP resistance, respectively." (PMID 40217758, 2025). "Diabetes insipidus results from either a partial or complete deficiency of circulating plasmatic AVP (CDI), or from partial or complete resistance of the distal nephron to AVP (NDI)." (PMID 40160705, 2025). "Arginine vasopressin disorders, especially vasopressin deficiency (central diabetes insipidus), commonly result from neurohypophyseal damage during cranial surgery." (PMID 40351988, 2025). "Distinguishing arginine vasopressin (AVP) deficiency (central diabetes insipidus) from primary polydipsia is challenging." (PMID 40281371, 2025). "Arginine vasopressin deficiency (central diabetes insipidus) results from impaired hypothalamic-neurohypophyseal secretion of arginine vasopressin and leads to hypotonic polyuria and polydipsia." (PMID 40123924, 2025). "Central diabetes insipidus is a clinical syndrome caused by the loss of function of vasopressinergic neurons in the hypothalamus, which results in impaired secretion of arginine vasopressin (AVP)." (PMID 39544593, 2024). "On the other hand, AVP deficiency can induce disorders associated with immune response; for instance, the Brattleboro rat strain developed diabetes insipidus (DI) because of mutations in genes that regulate the production of AVP." (PMID 36998727, 2023). "With cranial diabetes insipidus (cDI), there is a deficiency of antidiuretic hormone (ADH), also known as arginine vasopressin (AVP) following damage to the hypothalamus or posterior pituitary, resulting in an inability to retain water and concentrate urine." (PMID 37002645, 2023). "Central diabetes insipidus (DI) is characterized by a deficiency in arginine vasopressin (AVP), an antidiuretic hormone leading to excessive free water loss in the urine and hypernatremia." (PMID 36274908, 2022). "Diabetes insipidus is characterized by the excretion of large volumes of dilute urine due to vasopressin deficiency, arginine vasopressin (AVP) resistance, or excessive water intake." (PMID 34444990, 2021). "Another type of transport protein disorder affecting urinary concentration includes diabetes insipidus, caused by an impaired water permeability of the collecting ducts due to the inability of the kidneys to respond to arginine vasopressin (AVP) stimulation." (PMID 34204452, 2021). "Altered AVP signaling has been linked to diabetes insipidus, PKD, HF, and psychiatric conditions including ASD, bipolar, and borderline personality disorder." (PMID 33477721, 2021). "For example, deficiency or overproduction of hypothalamic AVP leads to the development of diabetes insipidus or metabolic problems, including obesity, hypertension, and multiple forms of diabetes, respectively." (PMID 33796071, 2021). "In this study, we investigated three-generations of a large Italian family with clinical diagnosis of familial central diabetes insipidus for the presence of potential pathogenic mutations in the AVP gene." (PMID 34319541, 2021). "In our opinion, the presence of diabetes insipidus, that is associated with low AVP/copeptin secretion, was the main factor responsible for lower copeptin concentrations in that group." (PMID 28795329, 2017).